SNX31 (sorting nexin 31)
Description:
May be involved in protein trafficking.
Synonyms: MGC39715
Tractability: No criterion of Open Targets' tractability assessment is met for any kind of drug.
Gene: Protein-coding gene on chromosome 8 (100,572,882 to 100,663,415, reverse strand). Ensembl gene ENSG00000174226.
Subcellular location (Human Protein Atlas): Golgi apparatus; Nucleoplasm; Cytosol
Gene Ontology:
Molecular function: protein binding; phosphatidylinositol binding
Biological process: endocytic recycling; intracellular protein transport
Cellular component: early endosome
Genetic constraint (gnomAD): Loss-of-function variants: 43 observed, 50.56 expected, observed/expected ratio (o/e) 0.85, 90% interval 0.67 to 1.1. The upper end of that interval is the gene's LOEUF score, 1.1, which puts it in group 4 of 6, group 1 being the genes least tolerant of losing a copy. Missense variants: 432 observed, 459.36 expected, observed/expected ratio (o/e) 0.94, 90% interval 0.87 to 1.02. Synonymous variants: 156 observed, 169.12 expected, observed/expected ratio (o/e) 0.92, 90% interval 0.81 to 1.05.
Homologues: Orthologues: chimpanzee SNX31 (99% identical), macaque SNX31 (90% identical), pig SNX31 (84% identical), rabbit SNX31 (80% identical), guinea pig SNX31 (78% identical), mouse Snx31 (75% identical), rat Snx31 (72% identical), dog SNX31 (68% identical), tropical clawed frog snx31 (42% identical). Paralogues in human: SNX17 (40% identical), SNX27 (20% identical).
Diseases named in the same sentence as SNX31 in open-access papers:
SNX31 is named in the same sentence as 7 diseases in open-access papers, as found by Europe PMC text mining. Sharing a sentence is not in itself a finding about the gene and the disease. The quoted sentences say what the papers report.
schizophrenia (1 paper, 2023). A major psychotic disorder characterized by abnormalities in the perception or expression of reality. "In 2014, studies found that mutations in the SNX31 gene can lead to schizophrenia." (PMID 37053012, 2023).
tumor (1 paper, 2020). "Copy number alterations were retained across several tumor-organoid pairs include CDKN2A, ERBB2, NF1, and SNX31." (PMID 32774159, 2020).
SNX31 also shares sentences with these, for which no sentence is quoted: melanoma (2 papers); cancer (1); familial melanoma (1); nodular melanoma (1); superficial spreading melanoma (1).